LEP (leptin)
Diseases named in the same sentence as LEP in open-access papers (continued):
Sharing a sentence is not in itself a finding about the gene and the disease.
Obesity (continued). "Leptin is elevated in obesity, and there is often central and peripheral leptin resistance in obese individuals, resulting in diminished energy expenditure and increased appetite." (PMID 40985048, 2025). "Recent years have seen growing interest in the development of anti-obesity drugs targeting leptin and adiponectin." (PMID 39897330, 2025). "Studies indicate that obesity induces increased PD‐1 expression on T cells through leptin‐dependent mechanisms, impairing T‐cell function and leading to T‐cell exhaustion." (PMID 41267926, 2025). "Chronic hyperleptinemia in conditions such as obesity can induce leptin resistance, disrupt normal signaling, and sustain a proinflammatory state." (PMID 41516046, 2025). "Caloric restriction and subsequent weight loss have been associated with increased orexin levels—known to influence wakefulness and nociceptive modulation—and decreased leptin levels, which are often elevated in obesity and have pro-inflammatory properties." (PMID 40426647, 2025). "In addition, partial mediating effects meant that BMI was also engaged in the pathogenesis of CRS through other pathways, which may be related to the obesity-induced state of systemic low-grade inflammation, and leptin, lipocalin, and other obesity-associated inflammatory factors." (PMID 40722081, 2025). "This protective capacity is diminished in individuals with leptin resistance, a common metabolic disturbance in obesity." (PMID 41226331, 2025). "Iron can alleviate obesity by regulating leptin levels and enhancing thermogenic capacity in adipose tissue." (PMID 41141252, 2025). "In states of obesity, circulating LEP concentrations are often elevated, reflecting the increased adipose tissue mass, but this hyperleptinemia is commonly accompanied by LEP resistance, where its physiological effects are diminished." (PMID 40586327, 2025). "Experimental models of obesity further demonstrate that leptin sensitizes macrophages to LPS, thereby promoting enhanced cytokine release, mitochondrial remodeling, and glycolytic metabolism through mTORC2-dependent pathways." (PMID 41516046, 2025). "Obesity drives Th2-type (eosinophilic) or Th17-type (neutrophilic) inflammation in asthma through an imbalance between pro-inflammatory factors (leptin, TNF-α, IL-6) and anti-inflammatory factors (adiponectin) secreted by adipose tissue." (PMID 41244254, 2025). "Obesity alters the secretion of adipose-derived hormones such as leptin, adiponectin, and resistin, and these imbalances have profound effects on metabolic homeostasis and cardiovascular health." (PMID 41282294, 2025). "Mice with global ablation of LGR4 demonstrate a decrement in adiposity and resistance to dietary and leptin mutant-induced obesity." (PMID 40069508, 2025). "Leptin, a hormone secreted by adipocytes, is significantly elevated in metabolic syndrome patients due to obesity and accelerates the progression of CRLM through activation of its receptor (LepR)." (PMID 41164182, 2025). "Adipokines, such as leptin and resistin, secreted by hypertrophic adipose tissue in obesity, enhance Th1 and Th17 polarization, contributing to pro-inflammatory cytokine production that disrupts microbial homeostasis." (PMID 39858932, 2025). "The impaired transport of leptin across the blood–brain barrier and disrupted intracellular signaling due to chronic inflammation in obesity further underscore its intricate involvement in reproductive function." (PMID 38398459, 2024). "Exciting studies performed in ob/ob and db/db mouse models of obesity led to this discovery, and profoundly influential studies in obese humans stimulated interest in leptin as a rational therapy for obesity and its numerous associated disorders." (PMID 38397458, 2024). "In our study, we found that leptin is raised in colon cancer-induced rats and obesity-induced colon cancer rats, while PB was able to suppress these changes." (PMID 39845239, 2024).
Obesity (continued). "M1-macrophages release high levels of TNF-α in obesity which, in turn, provide an inflammatory stimulus that increases the production of IL-6, leptin and plasminogen activator inhibitor-1 (PAI-1)." (PMID 38133765, 2024). "The most interesting finding in this study was that serum CES1 levels were significantly associated with lipid metabolism (ALT, AST, TG, TC, LDL-C), glucose metabolism (FBI, HOMA-IR) and obesity-related secreted proteins (adiponectin, leptin, GDF15, IGF-1)." (PMID 39227971, 2024). "Adipose tissue dysfunction in obesity has been associated with impaired metabolic health and altered hormone release, including leptin, which plays a role in both obesity and metabolic disorders." (PMID 39560873, 2024). "The results indicate that zeaxanthin effectively inhibits weight gain and leptin resistance in obese mice, thereby alleviating obesity and offering therapeutic benefits for IR." (PMID 39517172, 2024). "Leptin is an anorexigenic peptide hormone primarily produced by the adipose tissue and is elevated in obesity." (PMID 39493777, 2024). "The concept of leptin resistance has been studied mostly in the field of obesity but is also thought to affect cognitive abilities and depression." (PMID 39716315, 2024). "The unregulated endocrine function of adipose tissue in individuals with obesity leads to the dysregulated release of various adipokines, including leptin, ghrelin, and resistin." (PMID 39692821, 2024). "Leptin, a hormone primarily secreted by adipose tissue, presents another intriguing avenue of investigation when exploring the relationship between obesity and airway epithelial remodeling." (PMID 38562155, 2024). "Leptin, recognized as a pivotal factor in obesity-induced chronic inflammation, assumes a significant role in the intricate interplay of molecular events associated with OSA." (PMID 38562155, 2024). "Notwithstanding the large literature on this topic, the role of leptin signaling in thyroid dysfunction, and particularly in obesity-related hyperthyrotropinemia, is still highly controversial." (PMID 38417259, 2024). "Obesity is commonly accompanied by insulin and leptin resistance, impairing neuroprotective signaling pathways." (PMID 39456690, 2024). "The hyperleptinemia observed in common obesity, polycystic ovary syndrome (PCOS) and type 2 diabetes mellitus (T2DM) can be associated with central leptin resistance and have a direct impact on the gonads." (PMID 39273337, 2024). "Leptin is an adipokine affecting the regulation of appetite and energy homeostasis, and its plasma level is upregulated in obesity in proportion to adiposity, according to review article." (PMID 39036605, 2024). "One suggestion is the influence of obesity-related hormones, such as leptin and adiponectin, as well as the macrophage-specific metabolite itaconate, which exert cancer-promoting effects by affecting inflammatory gene expression via various pathways." (PMID 38611081, 2024). "A high-fat diet can up-regulate the hypothalamic expression of HDACs, which consequently induce obesity, affecting leptin sensitivity and resistance." (PMID 38892574, 2024). "The hormone leptin’s role in driving anti-obesity effects is well established, by binding to leptin receptors on POMC (anorexigenic) neurons." (PMID 38776045, 2024). "TNF-α, leptin, FFAs, and resistin are the components of adipose tissue remodeling in obesity that can contribute to oxidative stress-induced insulin resistance." (PMID 38892574, 2024). "Exercise training has been shown to reduce leptin levels in obese people, which makes sense given leptin’s function in obesity." (PMID 39125635, 2024).
Obesity (continued). "Previous studies have observed higher concentrations of inflammatory markers such as CRP, interleukin-6, leptin, and hepcidin in women with obesity compared with normal weight." (PMID 39255312, 2024). "Monogenic obesity is severe early-onset obesity due to a single gene in the leptin–melanocortin signaling pathway." (PMID 39519366, 2024). "In obesity, the initially elevated TSH and leptin levels usually decrease with weight loss, demonstrating a positive correlation." (PMID 39027638, 2024). "Analysis of the relationship between obesity and hand OA excluded the effect of physical load and revealed the role of leptin." (PMID 39229323, 2024). "We observed significant upregulation of proteins like COL1A1, COL6A3, FABP4, and LEP in individuals with obesity, indicating potential roles in adipose tissue dysfunction and metabolic dysregulation." (PMID 38732002, 2024). "In contrast, leptin resistance in obesity characterized by increased leptin/adiponectin ratio diminishes favourable cardiovascular outcomes in these patients." (PMID 39514148, 2024). "The increased leptin secretion in men with obesity can inhibit testosterone production by Leydig cells." (PMID 38892561, 2024). "Due to its ability to inhibit hunger and induce satiety, leptin has been considered an important factor in treating obesity." (PMID 39281006, 2024). "Impaired leptin signalling in both models was shown to result in severe obesity, hyperphagia and compromised glucose metabolism." (PMID 38580672, 2024). "Obesity is accompanied by hyperleptinemia with leptin resistance (due to impaired leptin receptor signaling and leptin insensitivity at the BBB or an impaired and saturated transport through the BBB) and hypoadiponectinemia." (PMID 39684351, 2024). "The most common monogenic form of obesity is associated with mutations in the MC4R gene, followed by mutations in the LEPR, POMC, PCSK1, and LEP genes." (PMID 39777073, 2024). "The research related to obesity and hypothyroidism is gradually gaining attention, and the research direction is gradually expanding to metabolic syndrome, insulin resistance, leptin, and other related topics." (PMID 38181287, 2024). "This study aimed to evaluate the association between dietary fat consumption and its influence on interleukin (IL) and leptin levels in participants with obesity." (PMID 39700087, 2024). "In circumstances of both obesity and malnutrition, alterations in leptin have correlated with shifts in immune function." (PMID 38332987, 2024). "Leptin plays a pivotal role in bridging the pathogenesis of psoriasis and obesity by enhancing angiogenesis in psoriatic lesions, augmenting keratinocyte proliferation, and increasing the secretion of pro-inflammatory protein." (PMID 38550599, 2024). "Both PD-1 ligation and enrichment of leptin in mammary tissues can activate STAT3 signaling in tumor-infiltrating CD8+ T cells, driving increased FAO, which is critical for obesity-associated breast tumor progression." (PMID 39402302, 2024). "Adipose tissue develops resistance to insulin and leptin and is the source of altered hormone and molecule release for adiponectin, which worsens obesity-related cardiovascular disease." (PMID 38899161, 2024). "Specifically, obesity alters hormones such as adiponectin and leptin, affecting all levels of these hormones within the hypothalamic-pituitary-gonadal (HPG) axis." (PMID 39623508, 2024). "One of the hallmarks of obesity is an increase in leptin-resistant adiposity, which consequently leads to adipocyte dysfunction." (PMID 39109269, 2024). "In summary, elevated leptin levels contribute to reduced signaling response in obesity, leading to leptin resistance." (PMID 38933275, 2024). "LEP encodes the hormone Leptin which plays a central role in energy homoeostasis including appetite regulation and mutations in LEP can contribute to the development of obesity and diabetes type 2." (PMID 38484284, 2024).
Obesity (continued). "In obesity, the liver plays a central role in the metabolism of blood lipids and is influenced by leptin resistance." (PMID 38623207, 2024). "A cross-sectional study reported that the levels of leptin hormone correlated with obesity and T2DM, and high serum leptin level was associated with the risk of developing both metabolic disorders." (PMID 39273348, 2024). "BPA is also capable of acting on the thyroid axis, affecting biomarkers related to obesity such as adiponectin, leptin, and ghrelin." (PMID 39519574, 2024). "In obesity, there is an imbalance in adipokine production, with increased production of pro-inflammatory adipokines such as leptin and decreased production of anti-inflammatory adipokines such as adiponectin." (PMID 39045323, 2024). "We used the terms “obesity”, “genetics”, “monogenic”, “syndromic”, “drugs”, “autosomal dominant”, “autosomal recessive”, “leptin-melanocortin pathway”, and “children” in different combinations." (PMID 38397265, 2024). "Obesity signals (such as leptin) function as potent inducers of the LIF, the most pleiotropic member of the interleukin-6 family of cytokines." (PMID 39518071, 2024). "The role of leptin in the ovary in relation to obesity-related infertility has been a matter of ongoing debate in recent years." (PMID 38398459, 2024). "Leptin primarily transmits nutritional feeding signals to the hypothalamus, resisting obesity onset by reducing appetite and promoting energy expenditure." (PMID 39456156, 2024). "Leptin and adiponectin are the most extensively studied adipokines in obesity-related cancers and there has been increasing interest in recent years toward new adipokines such as resistin and visfatin." (PMID 38255203, 2024). "Collectively, these clinical trials highlight an increasing interest in utilizing leptin sensitizers to tackle not only obesity and metabolic disorders but also neurological conditions." (PMID 39594988, 2024). "The leptin/adiponectin ratio is suggested to be altered in obesity, therefore we measured these proteins in adipocyte-conditioned media." (PMID 39339753, 2024). "Altered levels of adipokines such as leptin and adiponectin, oxidative stress, and inflammation are several obesity‐ and MetS‐induced mechanisms involved in changes in renal physiology and metabolism." (PMID 38268305, 2024). "Individuals with obesity frequently have higher adipokine levels in their bodies, such as leptin in the serum." (PMID 39906897, 2024). "Since a large population of the world is considered obese, there has been a vast amount of research conducted on the effect of obesity on adipokine secretion, specifically leptin, adiponectin, visfatin, apelin, and resistin." (PMID 39596205, 2024). "The C57BL/6J (B6) mouse strain presents rapid gains in body weight, often associated with the establishment of insulin and leptin resistance when exposed to a high fat diet (HFD), being therefore frequently classified as obesity prone (OP)." (PMID 39536822, 2024). "This leptin resistance is a key factor in the pathogenesis of obesity, as it undermines the body’s ability to regulate weight effectively." (PMID 39700087, 2024). "In general, studies show either a decrease in or maintenance of leptin levels in individuals with obesity after a meal." (PMID 39771019, 2024). "Obesity is known to increase proinflammatory cytokines (including interleukin-6 and tumor necrosis factor alpha in the adipose tissue) and leptin (a proinflammatory adipokine) and to decrease adiponectin, leading to dysfunction of innate immunity." (PMID 38557479, 2024). "Hormonal imbalances induced by obesity, such as altered levels of lipofuscin and leptin, also have a direct or indirect effect on vascular calcification." (PMID 39377074, 2024). "Obesity treatment is an enormous unmet medical need for which leptin initially appeared a logical answer, and development of leptin for treatment of obesity was aggressively pursued." (PMID 38165042, 2024).
Obesity (continued). "Adipose tissue in obese individuals secretes various adipokines, such as leptin, resistin, and visfatin, which are dysregulated in obesity." (PMID 39456690, 2024). "Consistent with previous research, one of our previous studies revealed that hypothalamic resistance to circulation hormones, such as leptin, contributes to obesity." (PMID 38965454, 2024). "Certain genetic polymorphisms with leptin and adiponectin secretion (LEP and ADIPOQ genes) have been linked to the obesity-associated asthma phenotype." (PMID 39272654, 2024). "Some components of adipokines, including leptin, adiponectin, resistin, Interleukin-6 (IL-6), and Tumor Necrosis Factor-α (TNF-α), have been associated with the development of insulin resistance, obesity, and related health conditions." (PMID 39457458, 2024). "T2DM patients with obesity commonly experience leptin resistance, and there is evidence of the therapeutic potential of leptin due to its glucoregulatory and antidiabetic actions based on clinical trial results." (PMID 39767690, 2024). "This approach not only helps us explore the physiological roles of leptin but also has potential value in the development of therapeutic strategies for obesity and related conditions." (PMID 39916981, 2024). "As for the connection of vaspin with other adipokines, vaspin concentrations correlated positively with adiponectin concentrations in subjects with obesity, and changes in vaspin correlated negatively with leptin concentrations." (PMID 39519480, 2024). "Obesity is accompanied by the expansion of adipose tissue, which results in increased levels of leptin in the bloodstream as well as the oxidation of LDL cholesterol and the secretion of inflammatory cytokines." (PMID 38732125, 2024). "In this study, we analyzed plasma leptin measurements from 18 women with premenopausal obesity before and after bromocriptine treatment." (PMID 39281006, 2024). "In recent years, leptin has been widely studied in obesity and anorexia nervosa, and its plasma levels are related to BMI." (PMID 39722796, 2024). "These intriguing observations of increased GLP-1 and leptin levels in control males compared with VS males indicate further investigation is needed using longer term murine obesity models to identify physiological significance." (PMID 38743047, 2024). "Not only is leptin upregulated in patients with obesity, but high leptin expression is also correlated to poor prognosis in several cancers, including thyroid, ovarian, prostate, and breast." (PMID 39596205, 2024). "Three companies developed leptin analogs for potential use in obesity, and the failure of studies of these analogs to produce sufficient clinical benefit caused these efforts to be terminated." (PMID 38165042, 2024). "Intriguingly, individuals with diet-induced obesity show significantly elevated levels of circulating leptin and are hyperleptinemic." (PMID 39872508, 2024). "Circulating leptin levels are positively correlated with BMI and adiposity, and their levels are significantly higher in obesity." (PMID 38672227, 2024). "We address some of the reasons here, beginning with our understanding of obesity and leptin in rodents." (PMID 38165042, 2024). "Studies have also demonstrated that probiotics that produce short-chain fatty acids (SCFA) exhibit anti-obesity properties by regulating lipid and glucose metabolism, reducing adipocyte size, lowering cholesterol, and regulating leptin levels." (PMID 39323881, 2024). "Additionally, BPA’s interaction with estrogen receptors can interfere with leptin and adiponectin signaling, two hormones involved in energy balance and insulin sensitivity, further promoting metabolic dysfunction and increasing susceptibility to weight gain and obesity." (PMID 39519574, 2024). "Despite high circulating leptin levels, this hormone is unable to function properly during obesity, leading to a state of leptin resistance." (PMID 38716728, 2024).